TNF (tumor necrosis factor)
Diseases named in the same sentence as TNF in open-access papers (continued):
Sharing a sentence is not in itself a finding about the gene and the disease.
colitis (continued). "We describe here for the first time, the effects of TNF ablation on acute TNBS colitis and the microbiota." (PMID 25775453, 2015). "Here we use wildtype (WT) and mice lacking Tnf (Tnf-/-) in an acute TNBS colitis model to investigate the role of TNF in colitis and how its presence or absence affects the colonic microbiota." (PMID 25775453, 2015). "Here, we show that single intragastric treatment with curli fibres ameliorates TNBS-induced colitis pathology to a similar degree as treatment with anti-TNFα antibody." (PMID 26855788, 2015). "As expected, we found that TNF promotes acute TNBS colitis, and CCA indicated colitis scores corresponded with alterations in the colonic microbiota." (PMID 25775453, 2015). "Plasma levels of proinflammatory cytokines IL-1β, TWEAK, and TNF-α were significantly elevated in animals with TNBS-induced colitis (P < 0.02) in comparison with intact rats." (PMID 25684862, 2015). "Our data also showed high levels of IL-1β, IL-6 and TNF-α in homogenates of colonic segment from mice with TNBS-induced colitis." (PMID 25853847, 2015). "In dextran sodium sulphate (DSS) induced colitis in mice, Embelin reduced the mRNA expression of TNF-α, IL-1, IL-6, and colonic MPO." (PMID 26347311, 2015). "For example, TNFΔARE mice that express a stabilized TNF transcript and spontaneously develop colitis, showed delayed onset and attenuated progression of IBD when crossed onto the Tpl2−/− background." (PMID 25781948, 2015). "In contrast, DSS-induced colitis switches from Th1/Th17-mediated acute inflammation (increased TNF-alpha, IL6, IL-17, and KC) to a predominant Th2-mediated inflammatory response in the chronic state." (PMID 25756273, 2015). "Current regimens utilized to combat inflammation in colitis include anti-TNF and anti-IL-6 therapies." (PMID 26448758, 2015). "Recently we demonstrated that brain stimulation of the CAP alleviates the disease severity and suppresses colonic proinflammatory cytokine (IL-6, IL-1β and TNF-α) levels in experimental DSS-induced colitis." (PMID 25295619, 2014). "IL-6 and TNFα expression levels were increased in all treatment groups following DSS-induced colitis; however, the largest increases were observed in WTWTBM mice." (PMID 25460165, 2014). "There were significant increases on IL-2 and TNF-α levels in colon of untreated colitis mice as compared with those of the normal mice and the ERC-treated colitis mice (#p < 0.01)." (PMID 25475342, 2014). "Antibody against TNF-α attenuates colitis in IBD patients, but more than one third of IBD patients do not respond to anti-TNF-α therapy." (PMID 24586980, 2014). "DUOX2 expression was also increased; however, this increase was moderate as compared to that of NOX1, suggesting a predominant role of NOX1 in TNFα-induced colitis." (PMID 25276054, 2014). "As DUOX2 homologue of NADPH oxidase is known to be expressed in the colon, although at a lower level than NOX1, we next investigated DUOX2 expression during TNFα-induced colitis." (PMID 25276054, 2014). "M. and P. can significantly improve the inflammatory process in the colonic mucosa in TNBS colitis aggravated by orally administered I. P. has a stable anti-TNF-α effect." (PMID 24895596, 2014). "Along with the increased ROS production, we show that the levels of endogenous antioxidants in colonic tissue, that is, glutathione and catalase, were decreased in our experimental model of TNFα-induced colitis." (PMID 25276054, 2014). "When treated with p38 inhibitor, mucosal IL-1β and TNF-α levels were reduced in DSS colitis model consistent with what we found for E.faecalis treatment." (PMID 24830946, 2014). "In particular, CO-RM ameliorates DSS-induced colitis by inhibition of neutrophil infiltration and TNF-α production." (PMID 24586391, 2014). "Here, we investigated the role of NOXs derived-ROS in a mouse model of colitis induced by the proinflammatory cytokine, tumor necrosis factor-α (TNF-α)." (PMID 25276054, 2014).
colitis (continued). "Further studies are warranted to investigate the effect of XLS on these proinflammatory cytokines, such as IL-6, IL-17, and TNF-α in colitis." (PMID 25120575, 2014). "The administration of polyphenols significantly suppressed the DAI score, along with reducing the histological severity of colitis and downregulating the expression of pro-inflammatory signaling factors, such as TNF-α, IL-1β and IL-6." (PMID 25409433, 2014). "We have investigated the production of cytokines including IFN-γ, IL-1β, IL-6, IL-10, IL-12 (P40), IL-12 (P70), IL-17, and TNF-α in colonic mucosa of mice with experimental colitis." (PMID 24948848, 2014). "Expression of all of the subunits forming the NOX1 system, namely, NOX1, p22PHOX, NOXA1, and NOXO1, was indeed increased in the mouse model of TNFα-induced colitis." (PMID 25276054, 2014). "A study of colitis in a mice model has shown RVs from the D-series can reduce production of pro-inflammatory cytokines such as TNF-α and IL-1β, similarly to the effects RV-E1 demonstrates in colitis." (PMID 24580770, 2014). "Studies of colitis in a mice model have demonstrated that treating with RV-E1 reduced leukocytes amount, reduced production and secretion of IL-12, TNF-α and other pro-inflammatory cytokines and decreased filled goblet cells." (PMID 24580770, 2014). "To elucidate the mechanism underlying the therapeutic effect of hHGF, we studied the expression of TNF-α and IL-1β in the colon and evaluated the inflammation and crypt scores at days 4, 7, 10 and 14 of the experimental colitis model." (PMID 24604303, 2014). "Our study demonstrates that apocynin treatment resulted in a marked improvement of the damage score and lower MPO activity in TNFα-induced colitis." (PMID 25276054, 2014). "Taken together, our present data showed, for the first time, that a marine hydroquinone can play a pivotal role in protecting against both colitis and apoptosis, decreasing the activity of UC, at least partially by inhibiting the TNF-α signaling pathway." (PMID 25409433, 2014). "This is in line with other studies, showing that macrophages from hIL-37Tg mice produce less TNF and that IL-37 overexpression reduces TNF-dependent inflammation in a murine model of colitis." (PMID 25620965, 2014). "Reduced colitis correlated with lower recruitment of neutrophils (p = 0.0018), as well as decreased production of IL-6 (p<0.0001), TNF (p = 0.0038), and IFN-γ (p = 0.0478)." (PMID 24992040, 2014). "Our previous studies demonstrated that PG reduces TNF-α production and induces Foxp3+ Treg cells in colitis and EAE mouse models." (PMID 25032213, 2014). "As in DSS colitis, the Ly6Chi monocytes elicited by T. gondii infection produce the proinflammatory cytokines TNFα and IL12, as well as reactive nitrogen species." (PMID 24726741, 2014). "Dietary arginine or glutamine supplementation had significant (P<0.05) influence on the clinical and biochemical parameters (T-SOD, IL-17 and TNF-α) in colitis model." (PMID 24505477, 2014). "Consistent with this, a mutation that inactivates PI3Kγ enzymatic activity (‘kinase-dead’) leads to less severe colitis in mice, which produce significantly more pro-inflammatory Th1 cytokines, such as IL-12, TNF-α, and IFN-γ." (PMID 24586980, 2014). "In the GC-C gene KO mice with chemical-induced colitis, apoptosis, TNF-α, and IFN-g levels in intestinal epithelial cells were significantly reduced." (PMID 24992336, 2014). "Severe colitis was mediated by increased local expression of cytokines (IL-6, IL-10, TNF-α, IFN-γ and IL-17A) and phosphorylation of Leucine-rich repeat kinase 2 (LRRK2)." (PMID 24873968, 2014). "TNFα-induced colitis was characterized by a substantial neutrophil infiltration, as shown by the presence of MPO activity in the inflamed colon." (PMID 25276054, 2014). "In mice, IL-19 up-regulates TNFα and IL-6 expression and its deficiency increases susceptibility to DSS-induced colitis." (PMID 24718601, 2014).
colitis (continued). "In the current case, infliximab was successful to control the intestinal bleeding in acute phase, suggesting that similar to classic Crohn’s disease, anti-TNF alpha therapy can also induce rapid effect to control severe symptoms in CVID-related colitis." (PMID 24952714, 2014). "We found significantly reduced TNF-α production locally, despite the clear differences in colitis severity between BF-DSS and GF-DSS mice." (PMID 24971344, 2014). "This compound inhibits inflammation in in vitro and in vivo models, including anti-inflammatory effects on aortic smooth muscle exposed to TNF-α, the colon of colitis mice, and brain tissue in an cerebral ischemia animal model." (PMID 24675731, 2014). "TNFα-induced colitis was also characterized by high production of keratinocyte-derived chemokine (KC) and mucosal infiltration of neutrophils, NOX2-expressing cells." (PMID 25276054, 2014). "Although R243 treatment reduced IL-10 secretion, its overall suppression of TNF-α and IL-6, together with inhibition of inflammatory cell infiltration, seemed to ameliorate colitis." (PMID 24714157, 2014). "A p38 inhibitor suppressed inflammation in DSS-induced colitis model by reducing mucosal IL-1β and TNF-α levels." (PMID 24830946, 2014). "This study demonstrates for the first time that TNFα-induced colitis triggers a marked increase in the expression of key components of the colon-specific NADPH oxidase isoform, NOX1, NOXA1, NOXO1, and p22PHOX." (PMID 25276054, 2014). "Overproduction of proinflammatory cytokines, including TNF-α, IL-1β, and IL-6, is observed in several animal colitis models." (PMID 24995035, 2014). "Mucosal TNF-α is necessary for the initiation and perpetuation of TNBS colitis, since TNF-α-deficient mice are resistant to TNBS, and the colitis is extremely severe in mice that overexpress TNF-α." (PMID 24895596, 2014). "The leukocyte infiltration into the mucosa and submucosa of the small intestine of mice with colitis at 6 DPI was associated with increased concentration of IL-6, IL-12p70, IL-10, IL-22 MCP-1 and TNF-α, IL-1β, MPO but lower concentration of IL-17A." (PMID 24167594, 2013). "IL-10 is an important anti-inflammatory factor secreted by mononuclear cells and macrophages in colitis, which can suppress inflammatory reaction and decrease the secretion of pro-inflammatory cytokines such as IL-1β and TNF-a." (PMID 23874391, 2013). "In our study, atorvastatin decreased production of IL-17 and intracellular expression of IFN-γ, in agreement with data from a Lewis rat model of experiment autoimmune neuritis and in Balb/c mice with experimental colitis, in which TNF-α was also downregulated." (PMID 24159421, 2013). "Treatment of mice with DSS-induced colitis with rivastigmine (1 mg/kg) for 8 days almost completely prevented the release of TNF-α from macrophages harvested from the mice and activated by LPS." (PMID 23469045, 2013). "Colitis increased TNFα levels in blood circulation and sulfasalazine was most effective in normalizing TNFα release (vs. colitis p < 0.01)." (PMID 23761791, 2013). "Upon colitis induction, a significantly increased level of TNF-α was present in the colon of SIGNR3−/− mice compared to wild-type mice." (PMID 23882266, 2013). "Since TNFR1 mediates TNF-α induced NF-κB activation and is crucial for murine colitis induction, subsequently we investigated the effect of lentinan on the receptor." (PMID 23630633, 2013). "We then evaluated the expression of TNF-α, IL-1β, and IL-6 from each fraction to determine their relative contributions to mesenteric cytokine expression during acute colitis." (PMID 24386254, 2013). "The suppressant effect of TU-100 on mucosal damage, mucosal ischemia, and especially TNF-α production was shown in TNBS-induced colitis in an ADM-dependent manner." (PMID 24348533, 2013). "Recently, it has been demonstrated that TNF downregulates Klotho (KL) through the nuclear factor kappa B (NFkB) system in animal models of chronic kidney disease and colitis." (PMID 23634661, 2013).
colitis (continued). "It has been shown that selective blockade of TNF-α and IL-6 significantly decreases the severity of colitis and neutrophil/macrophage migration." (PMID 23818935, 2013). "Guanylin was diminished early in colitis in vivo and tumor necrosis factor α suppressed guanylin mRNA and protein in intestinal goblet cell-like HT29-18-N2 cells." (PMID 24244444, 2013). "The DSS-induced colitis model has contributed to identify candidate drugs and drug targets, including TNF-α, which is now an established therapeutic target in human IBD." (PMID 23638016, 2013). "The levels of the inflammation-related cytokines IL-6 and TNF-α were used to determine the preventative effects on dextran sulfate sodium (DSS)-induced colitis in mice." (PMID 24223664, 2013). "These series of experiments document the ameliorating effect of roflumilast and pumafentrine on the clinical score and TNF expression of experimental colitis in mice." (PMID 23468885, 2013). "Inflammatory cytokines such as IL-6, TNF-α, and interferon-γ mediate the pathogenesis of murine colitis." (PMID 24194783, 2013). "During acute colitis, TNF-α expression in the MAT was equivalent per unit of RNA to that of the colon, and significantly greater (P<0.001) than the other adipose tissue depots." (PMID 24386254, 2013). "TNBS-colitis is an appropriate IBD-model to study specific biological processes like TNF signaling, Cell junction organization, and Interleukin-1 processing." (PMID 23382912, 2013). "AhR−/− mice are more sensitive to DSS colitis than WT mice while AhR−/+ mice are less sensitive and exhibit a decreased expression of TNF and IL-17 and an increased expression of IL-10 as we observed in our model." (PMID 23638007, 2013). "Pro-inflammatory cytokines such as TNF, IL-1 and IL-6, all regulated by the NF-κB pathway, have been shown to be overexpressed in colitis, gastritis, or hepatitis." (PMID 23117246, 2013). "Exacerbation of DSS colitis in SIGNR3−/− mice was accompanied by an increased TNF-α production in the colon suggesting that fungal recognition by SIGNR3 contributes to intestinal homeostasis." (PMID 23882266, 2013). "GSC extract significantly blocked TNF-α mRNA expression in colonic tissues of mice with DSS-induced acute colitis." (PMID 23841050, 2013). "Treatment with a TNF neutralizing antibody, a locally active TNF inhibitor, antisense oligonucleotides and siRNA molecules specific for TNF were shown to be effective in the DSS-induced colitis model." (PMID 23723167, 2013). "IL-10, which counteracts effects of proinflammatory cytokines such as tumor necrosis factor alpha (TNFα), prevents colitis in mouse models of human IBD." (PMID 24244309, 2013). "RvD1 has been shown to reduce levels of TNF-α and IL-6 in mouse models of colitis, d-galactosamine-sensitized endotoxin shock and ALI." (PMID 23199346, 2012). "Mice treated with VSL#3 or CLA showed improved DSS colitis that was associated with lower percentages of inflammatory macrophages expressing CCR2 (the receptor for MCP-1) and TNF-α in MLN." (PMID 22363592, 2012). "TNBS-induced colonic inflammation in mice is a commonly used chemically induced model that features up-regulation of pro-inflammatory cytokines (IL-1β, IFNγ, TNFα, IL-12, IL-17A)." (PMID 22461841, 2012). "We investigated the immune response in TRUC mice aged >12 weeks, an age at which TNF-α blockade loses efficacy and severe colitis emerges." (PMID 23063332, 2012). "Such a decrease in IL-1β was previously reported by Hirano and Kudo after treatment of CD45RB transfer colitis mouse model with both dexamethasone and anti-tumor necrosis factor-α (anti-TNF-α)." (PMID 23198878, 2012). "Using a murine model they discovered a protective role of IFN-α/β in experimental colitis as a result of cross-regulation mechanisms with TNF-α." (PMID 22723961, 2012). "In aggregate, our results indicate that hepcidin expression is inhibited during DSS colitis by a TNFα-dependent mechanism." (PMID 22675442, 2012).
colitis (continued). "TNF-α is crucial in the pathogenesis of colitis and the use of anti-TNF-α monoclonal antibodies is beneficial in IBD patients." (PMID 23109839, 2012). "We have identified Helicobacter typhlonius as a key disease trigger driving excess TNF-α production and promoting colitis in TRUC mice." (PMID 23063332, 2012). "Meanwhile oral administration of picroliv significantly reduced IL-1β, TNF-a mRNA expression increased in the clonic tissues of DSS-induced colitis by inhibiting the expression of NF-κB p65." (PMID 23125487, 2012). "In this report, we provide evidence that TNF signaling via TNF-R1 or 2 has opposite effects on the pathogenesis of DSS-induced colitis." (PMID 23285227, 2012). "Related to NDOs, beneficial role of βGM from partially hydrolyzed guar gum was described to prevent mucosal damage in dextran sulphate sodium (DSS) induced colitis in mice by a decrease of TNFα mRNA/protein and neutrophil infiltration." (PMID 22277078, 2012). "In this study, striking UC-like vs. CD-like phenotypic differences were observed in the distribution and histologic characteristics of colitis of Il10−/− mice based on changes in a single gene that affected TNF production." (PMID 22848611, 2012). "Compared to similarly aged, non-colitic Rag2 knockout mice, the isotype-treated TRUC mice with colitis displayed a trend (p = 0.07) towards lower hepcidin levels, while anti-TNFα treatment of the TRUC mice led to a significant increase in hepcidin." (PMID 22675442, 2012). "TNFα is expressed in this model at levels comparable to DSS colitis, and indeed anti-TNFα treatment attenuates the severity of the colitis in the αv integrin knockout mice." (PMID 22675442, 2012). "Taken together, our findings suggest that the inhibitory effect of TNFα on hepcidin expression during DSS colitis is mediated by down-regulation of Smad1 protein (and possibly Smad5 and Smad8) and consequent interference with BMP-activated signals." (PMID 22675442, 2012). "Expression and activation of Smad1, a positive regulator of hepcidin transcription, were assessed during colitis and following administration or neutralization of TNFα." (PMID 22675442, 2012). "Collectively, we found that CTLA4-Ig, anti-IL-12p40 mAb, and antibiotics prevented onset of colitis and cured established disease, while anti-TNF-α mAb, anti-IL-6 mAb, and anti-α4β7 mAb prevented onset of colitis but did not reverse established disease." (PMID 22536543, 2012). "It is worthy to note that the data presented in our study are incompletely consistent with a previous report that TNF signaling via TNF-R1 or 2 is redundant for the pathogenesis of DSS colitis in C57Bl/6 mice." (PMID 23285227, 2012). "TNFα inhibits hepcidin expression in two distinct types of innate colitis, with down-regulation of Smad1 protein playing an important role in this process." (PMID 22675442, 2012). "Its administration attenuated the development of signs and symptoms of colitis, reduced colonic expression of TNF-α, Interleukin (IL)-6, and IFN-γ, and reserved colonic down-regulation of PPAR-γ, PXR, and FXR caused by a TNBS model of induced colitis." (PMID 23251142, 2012). "The studies on the function of TNF signaling via TNF-R1 or 2 on the course of DSS-induced colitis, which is another widely used murine model of IBD and closely resembles UC, is relatively few." (PMID 23285227, 2012). "We have also identified a constituent of the TRUC intestinal microbiota that augmented colonic TNF-α production and triggered severe colitis in rederived, otherwise healthy, isogenic Tbx21−/−Rag2−/− hosts." (PMID 23063332, 2012). "We conclude that early onset colitis is dependent on TNF-α that preceded depletion of adherent and goblet cell mucin prior to epithelial cell damage and these biomarkers can be used as therapeutic targets for UC." (PMID 21949848, 2011).